SPOCK1 (SPARC (osteonectin), cwcv and kazal like domains proteoglycan 1)
Diseases named in the same sentence as SPOCK1 in open-access papers (continued):
Sharing a sentence is not in itself a finding about the gene and the disease.
cancer (continued). "The SPARC/osteonectin, CWCV and Kazal-like domains proteoglycan 1 (SPOCK1) is a proteoglycan which is involved in many types of cancer, including RCC." (PMID 37370817, 2023). "Among these DEGs, SPOCK1 and POSTN were identified as key prognostic genes and mainly expressed in cancer-associated fibroblasts for CRC." (PMID 36611136, 2023). "The pan-cancer analysis from the TCGA cohort also showed a correlation between SPOCK1 overexpression and poor prognosis in the majority of tumors." (PMID 38087364, 2023). "Then, using the TIMER database, we further investigated the correlation between SPOCK1 in pan-cancer and the infiltration levels of CD8+ T cells using multiple immune infiltration evaluation methods." (PMID 38087364, 2023). "Subsequent univariate Cox regression analysis demonstrated significant prognostic value of SPOCK1 in cancers such as LUAD, KIRC, and PAAD." (PMID 38087364, 2023). "While SPOCK1 expression was high in the cirrhotic hepatocytes, the staining intensity in cancer cells was heterogeneous." (PMID 35186754, 2022). "The extracellular matrix proteoglycan SPOCK1 is increasingly recognized as a contributor to the development and progression of cancers." (PMID 35186754, 2022). "Based on this background, we investigated if a) healthy or diseased hepatocytes express SPOCK1 and b) SPOCK1 plays a mechanistic role during hepatocarcinogenesis and cancer progression." (PMID 35186754, 2022). "Since the first study reported its oncogenic role in 2011, a number of accounts described the implication of SPOCK1 in the poor outcome in almost all types of cancers, from glioblastoma to prostate tumors." (PMID 35186754, 2022). "Although there is a possibility that miR-135/ SPOCK1 axis affects other pathways, our data establish a key role for miR-135 in the regulation of SPOCK1 homoeostasis activity, to promote cancer phenotype in murine PO and human tPDOs." (PMID 35046388, 2022). "SPOCK1 promotes the proliferation and migration of cancer cells, regulates the cell cycle and inhibits apoptosis through the PI3K/Akt pathway." (PMID 34003875, 2021). "The upregulation of SPOCK1 is also related to the advanced T stage or Gleason score of some cancers." (PMID 34003875, 2021). "SPOCK1 is a secreted proteoglycan reported to induce EMT in several cancer cell lines and up-regulate the expression and activity of MMP-9 24–26,37,38." (PMID 32555336, 2020). "SPOCK1, a representative target gene of miR-375, has been demonstrated to facilitate metastasis in certain types of cancer and to promote GC invasion and metastasis through a Slug-dependent mechanism." (PMID 32313120, 2020). "In conclusion, our study showed for the first time that SPOCK1 up-regulation induces EMT in a pathological condition other than cancer through several possible pathways and points to SPOCK1 as a novel therapeutic target for DIGO." (PMID 32555336, 2020). "SPOCK1, TGF-β1, and MMP-9 are associated with the EMT process in several cancer types so, we asked if these molecules are also involved in EMT-related DIGO." (PMID 32555336, 2020). "SPOCK1 is highly expressed in many types of cancer and has been recognized as a promoter of cancer progression." (PMID 33293473, 2020). "SPOCK1 is an extracellular proteoglycan that induces epithelial to mesenchymal transition (EMT) in several cancer cell lines and exhibits protease-inhibitory activity." (PMID 32555336, 2020). "In the present study, we found that SPOCK1, which is upregulated in PCa, is involved in the invasion and metastasis of cancer cells and was correlated with poor prognoses." (PMID 31182131, 2019). "More importantly, clinicopathologic analyses revealed that SPOCK1 is frequently overexpressed in PCa tissues, and is involved in cancer recurrence, drug resistance, and metastasis." (PMID 31182131, 2019). "As per our expectation, an advanced cancer stage was accompanied by a higher SPOCK1 score, and it showed an escalation with elevated Gleason grade." (PMID 31284511, 2019).
cancer (continued). "The SPOCK1 expression score was higher in advanced cancer stages compared with earlier cancer stages (254 ± 60, p = 0.020)." (PMID 31284511, 2019). "It is interesting to note that knockdown of SPOCK1 significantly attenuated cancer cell migration and invasive abilities." (PMID 31052206, 2019). "In normal prostate tissues, SPOCK1 generally displayed very light staining, whereas SPOCK1 was moderately and/or strongly positive stained in cancer samples." (PMID 31182131, 2019). "Although the role of SPOCK1 in cancers has been relatively well understood, its contribution to neurological and cognitive development remains elusive." (PMID 28155865, 2017). "A functional study showed that overexpression of SPOCK1 enhanced invasiveness in mammary immortalized and cancer cells." (PMID 27626636, 2016). "Even less is known about the function and mechanism by which SPOCK1 contributes to cancer development and progression." (PMID 25623055, 2015). "To investigate the effects of SPOCK1 on cancer cell migration and invasion, we performed in vitro wound healing and transwell migration assays, and an in vivo metastasis assay." (PMID 25623055, 2015). "The observed positive correlation between HOTAIR and SPOCK1 suggests that these genes may function synergistically in cancer progression." (PMID 40001977, 2025). "SPOCK1 has been reported to promote cancer metastasis in various types of cancer." (PMID 38087364, 2023). "Due to the limited research on SPOCK1 in cancer, we evaluated its expression at a pan-cancer level." (PMID 38087364, 2023). "Overall, SPOCK1 exhibited differential expression across various cancer types." (PMID 38087364, 2023). "In general, SPOCK1 expression is higher in tumors than in their non-tumorous adjacent tissues, as determined by a comprehensive analysis across different types of cancers, and its overexpression has been linked to poor clinical outcomes." (PMID 37046698, 2023). "In addition to its physiological functions, SPOCK1 is a critical regulator in many kinds of cancers, including CRC." (PMID 35046388, 2022). "Do cancer cells need more intracellular SPOCK1 for their functions?" (PMID 35186754, 2022). "Knockdown of SPOCK1 expression inhibits the invasion and metastasis of various cancer cells." (PMID 36397112, 2022). "In experimental hepatocarcinogenesis, syndecan-1 overexpression provides protection against the development of cancer, and in addition to other factors, the downregulation of SPOCK1 could be observed throughout the experimental period." (PMID 35186754, 2022). "Currently, a number of studies have shown that SPOCK1 acts as an oncogene in various cancers." (PMID 34003875, 2021). "Lastly, we define two candidate genes potentially regulated by pBRD4 in JQ1 resistant LAC, AXL and SPOCK1, which cancers may become dependent on after adaptation to BETi treatment, offering additional avenues for therapeutic intervention." (PMID 33712563, 2021). "Testican 1, encoded by SPOCK1 gene, has been shown to promote cancer growth." (PMID 33330449, 2020). "Therefore, SPOCK1 has been considered as a novel prognostic and therapeutic target for various cancer types." (PMID 28155865, 2017). "Moreover, although an oncogenic role of SPOCK1 has been demonstrated in multiple cancers, very little is known about the pathogenesis of SPOCK1 dysregulation." (PMID 27626636, 2016). "In addition, SPOCK1 promoted cancer cell migration and epithelial-mesenchymal transition by regulating the expression of relevant genes." (PMID 25623055, 2015). "Although SPOCK1 is reported to be overexpressed in several other types of carcinoma, it has not been linked to GBC or any other malignancy of the biliary tract." (PMID 25623055, 2015). "Moreover, SPOCK1 expression was significantly elevated (p = 0.002) in ERG-high cancers and that of FBLN1 was significantly diminished (p = 0.047)." (PMID 20860828, 2010).
cancer (continued). "In addition, comprehensive in vivo and in vitro studies including many individuals may create new strategies for cancer diagnosis and treatment by elucidating whether SPOCK1 can be used as a biomarker." (PMID 40001977, 2025). "Recent evidence showed that SPOCK1 overexpression was observed in several cancer types, such as prostate, colorectal, gastric, pancreatic, and lung cancers, and it was involved in modulating cancer cell proliferation, apoptosis, metastasis, and drug resistance." (PMID 36766694, 2023). "Therefore, SPOCK1 is a critical regulator in cancer progression." (PMID 35046388, 2022). "SPOCK1, due to its important roles in cancer, could serve as a potential therapeutic target." (PMID 36358747, 2022). "Our findings indicate that SPOCK1 may drive EMT in cancer cells, resulting in metastasis." (PMID 25623055, 2015). "Previous studies have shown that SPOCK1 is a key regulator of ECM and can mediate EMT in cancer cells." (PMID 36611136, 2023). "SPOCK1 has also been shown to stimulate the epithelial–mesenchymal transition (EMT), thus promoting cancer cell invasion, correlating directly with the expression of mesenchymal markers and, inversely, with epithelial markers." (PMID 37370817, 2023). "SPOCK1 has been shown to contribute to cancer cell invasion and metastasis through the promotion of EMT in multiple cancer types." (PMID 36358747, 2022). "Further stage plot analysis indicated an elevated expression of SPOCK1, across COAD cancer stages, relatively the highest expression in advanced stages." (PMID 35046388, 2022). "One oncogene, Sparc/osteonectin, cwcv, and kazal-like domains proteoglycan 1 (SPOCK1), was observed to affect the EMT process by facilitating metastasis in various cancers." (PMID 31182131, 2019). "Each guide strand and passenger strand coordinately regulates oncogenic genes as observed in several cancers, e.g., pre-miR-145: MTDH and UHRF1; pre-miR-139: MMP11; pre-miR-150: SPOCK1." (PMID 28902136, 2017). "Three cancers were analyzed for OS and RFS rates, as well as SPOCK1 expression." (PMID 40001977, 2025). "As examples, SPOCK1 protein was significantly lower in the soluble fraction of urine from cancer patients but not in uEVs, while PCYOX1 shows the inverse." (PMID 38871730, 2024). "SPOCK1, a glycoprotein isolated from human testes, is a member of the secreted, acidic, cysteine-rich (SPARC) family of extracellular matrix-resident proteins that play multiple roles in cancer progression, including EMT." (PMID 38791608, 2024). "SPOCK1 and OLR1 were chosen for assessment by immunofluorescence based on their significant differential expression in invasive organoids, transmembrane and intracytoplasmic protein localization, and previously reported roles in cancer cell invasion." (PMID 36881486, 2023). "Previous studies indicated that the SPOCK1-mediated EMT regulates proliferation and invasion via activation of the PI3K/Akt signaling pathway in several cancer types such as colorectal, gallbladder, pancreatic, and brain cancers." (PMID 36766694, 2023). "SPOCK1 (SPARC/osteonectin, cwcv and kazal-like domains proteoglycan 1), also referred to as testincan-1, is a crucial regulator of the dynamic balance of extracellular matrix (ECM) and mediates epithelial-to-mesenchymal transition (EMT) in cancer cells." (PMID 35433415, 2022). "SPOCK1, a secreted matricellular protein and also called SPARC, is a critical regulator of EMT induction and could be a novel therapeutic target for cancer progression." (PMID 35360859, 2022). "Among the remaining 8 DEGs (ADRA2A, P2RX6, XCL2, XCL1, CCL7, TRIM54, TNFRSF18 and SPOCK1), the expression of ADRA2A, the top one, in KIRC based on individual cancer is lower than the normal tissues, but patients with lower expressed ADRA2A have a better overall survival (OS)." (PMID 31159832, 2019).
cancer (continued). "In this study, we investigated the in situ expression patterns of the MEC marker, SPOCK1, in 478 IDC cases, as well as in 81 non-IDC histological carcinoma subtypes." (PMID 27626636, 2016).
cardiovascular disease (1 paper, 2012). "Using this approach, we have identified four candidate genes (EBF1, PPP2R2B, PRELID2, and SPOCK1) that may represent novel cardiovascular disease risk genes mediated through LDL cholesterol pathways." (PMID 22369142, 2012).
immune system diseases (1 paper, 2018). "DEGs that enriched to “immune system diseases” played critical roles in cell-matrix communication (THY1, LVRN, LUM, TIMP3, SPOCK1, LGALS3BP, FAT2, and SERPINE2) as well as inflammation (IL1R2, CD22, PTGES, TNFSF10, IL2RB, C3, SERPING1, and IL-17RE)." (PMID 30131724, 2018).
SPOCK1 also shares sentences with these, for which no sentence is quoted: esophageal squamous cell carcinoma (3 papers); pancreatic ductal adenocarcinoma (3); gall bladder carcinoma (2); aortic stenosis (1); developmental delay (1); diabetes (1); endocervical adenocarcinoma (1); endometrial cancer (1); epilepsy (1); gastric adenocarcinoma (1); gynecological tumors (1); Intellectual disability (1); invasive ductal carcinoma (1); invasive lobular carcinoma (1); leukaemias (1); liver cirrhosis (1); metaplastic breast carcinoma (1); mucinous carcinoma (1); multiple system atrophy (1); neurodegenerative disease (1); osteoarthritis (1); ovarian serous cystadenocarcinoma (1); personality disorder (1); primary immunodeficiency (1); progressive supranuclear palsy (1); pulmonary oedema (1); serous ovarian cancer (1); sickle cell anemia (1); thymoma (1); tubular carcinoma (1).
A further 2 diseases each share a sentence with SPOCK1 in 1 paper.